ATG7 (autophagy related 7)
Diseases named in the same sentence as ATG7 in open-access papers (continued):
Sharing a sentence is not in itself a finding about the gene and the disease.
tumor (continued). "Mice injected with A2780 cells co-transfected with ATG7 and HULC showed significantly lower rates of tumorigenicity after inoculation as compared with the HULC-ATG7-Mut group (P<0.05) and exhibited smaller tumor volumes during the same observation period." (PMID 29022892, 2017). "Regarding tumor cell survival, the resistance to metabolic stress induced by TMEM74 overexpression was counteracted by ATG5, ATG7, ATG16L1, ATG3 and ATG10 deficiencies but not the BECN1 and ULK1." (PMID 29048433, 2017). "Moreover, Beclin-1 and ATG7, which act downstream of ULK1, were also significantly upregulated in tumor tissues compared with the corresponding background tissues." (PMID 28079894, 2017). "Interestingly, tumor spheres expressed the significantly lower level of ATG5, ATG7, BECN1 and LC3B mRNAs." (PMID 27934912, 2016). "Despite that Beclin1 having been demonstrated as having a tumor-suppression function for autophagy, KO of Atg5, Atg7 and FIP200, other essential autophagy proteins, failed to initiate malignant tumor development in vivo." (PMID 27124579, 2016). "For example, gene inhibition of Atg5 or Atg7 has demonstrated that the absence of autophagy in tumor‐prone mouse models increases the incidence of precancerous lesions and tumors after activation of the RAS pathway, indicating that autophagy can prevent cancer development." (PMID 39648951, 2025). "Notably, although the ATG7 protein showed extensive nonautophagy-related effects, the role of ATG7 as an autophagy-regulatory gene in reshaping epithelial-stromal interactions to affect tumor progression should also be carefully considered." (PMID 40707430, 2025). "The results revealed that whereas ATG7 inhibition did not suppress CRC cell proliferation, it effectively caused an immune response for targeted tumor clearance in vivo, thereby highlighting the key role of CD8+ T cells in regulating the observed anti-tumor immunity in ATG7-deficient CRC." (PMID 38627815, 2024). "The generation of mice that express this short form of ATG7, but not full-length, would be very interesting and could be utilized to see if this short form retains the tumor suppressive function of ATG7 that is independent of LC3 conjugation as we report here." (PMID 35867735, 2022). "However, Atg7 hemizygosity also enhanced tumor initiation and progression, even though this did not ablate autophagy." (PMID 35867735, 2022). "Tumor-bearing animals formed metastasis regardless of Atg7 status." (PMID 35372352, 2022). "YFSJ remarkably reduced Atg16, Atg7 and LC3-2/LC3-1 ratio, significantly increasing the expression of P62, suggesting that YFSJ remarkably inhibited tumor autophagic activities and subsequently blocked autophagy flow, which was shown by the accumulation of P62." (PMID 35645820, 2022). "Specifically, ATG7 might play a role in tumor promotion, while ATG9B might be a tumor suppressor." (PMID 36262348, 2022). "Studies have shown that ATG7 adjusts three negative breast cancer tumor progressions." (PMID 34691238, 2021). "In addition, two out of the three tumor samples from Atg7/Hmgb1ΔHep livers were also close to the non-tumor samples whereas tumor samples from Atg7ΔHep mice were separated the farthest from the rest of the samples." (PMID 32382012, 2020). "Since Ulk1, Vps34, and Atg7 represent the key nodes of the autophagy pathway, these results indicate that the effects of Ppt1 inhibitors are independent of the autophagy pathway in tumor cells at least in the B16 model." (PMID 32780726, 2020). "Immunostaining analysis for PCNA showed a lower number of proliferating hepatocytes in the tumor and non-tumor regions of Atg7/Hmgb1ΔHep livers than those in the Atg7ΔHep livers, suggesting that HMGB1 contributed to an overall enhanced proliferation status in autophagy-deficient livers." (PMID 32382012, 2020).
tumor (continued). "Moreover, tumor size and number were significantly decreased in Atg7/Yap het DKO mice and Atg7/Yap DKO mice compared to Atg7 KO at 12 months after tamoxifen administration thereby identifying Yap as a driver of liver growth and hepatocarcinogenesis when autophagy is impaired." (PMID 30470740, 2018). "Importantly, Kras-driven tumors, which normally formed adenomas and carcinomas, diverted to more benign oncocytomas in the absence of Atg7, indicating that the functional status of autophagy determines the tumor fate." (PMID 30622432, 2018). "Furthermore, the detection of LC3 protein levels in the tumor tissue samples also verified that tumors from ATG7-knockout HCCLM9 cells did not undergo autophagy even when treated with tetrandrine." (PMID 29334999, 2018). "Moreover, we identify ATG7 overexpression results in reduction of FOXO1-dependent p27 transcription, thereby inhibiting the tumorigenic growth of BC cells, which highlights the tumor suppressor function of p27 in human BC growth." (PMID 28624205, 2017). "Notably, the xenograft mouse model showed that clone A of Atg5‐overexpressed Atg7−/− MEF cells induced temporal tumor formation, but could not prolong further tumor growth." (PMID 38826147, 2024). "In addition, silence of the Atg5 or Atg7 also did not sensitize tumor cells to other PI3Kis." (PMID 34844627, 2021). "Conversely, downregulation of ATG7 reduced m-THPC-PDT-induced autophagy in tumor tissues, as revealed by the m-THPC-PDT-induced increase in MAP1LC3B-II protein expression and a decrease in SQSTM1/p62 expression that could be counteracted by ATG7 downregulation." (PMID 33130826, 2020). "Taken together while the reason for the paradoxical elevation of AKT and JNK phosphorylation in Atg7/Hmgb1ΔHep livers is not clear these events do not seem to be tumor specific and may not be related to the reduced proliferation status of tumors from in these livers." (PMID 32382012, 2020). "Mice treated with TRI-03 presented a significant reduction in tumor weight, with a tumor growth inhibition rate of 74.0% (P < 0.01), However, TRI-03 had no significant inhibitory effect in the Atg7-shRNA group (P = 0.66)." (PMID 40486906, 2025). "Immunohistochemistry for ATG7, LC3 and p62/SQSTM1 established the presence/absence of autophagy and positivity for S100 confirmed melanocytic origin of tumour cells." (PMID 33664481, 2021). "On the other hand in mice, knockdown of Atg7 but not Becn1 decreased numbers of tumors formed by dormancy-prone cells in a TGFβ-induced inflammatory background, indicating that requirement for Becn1 gene in dormancy-related autophagy and tumor cell survival might be tumor and cell type-dependent." (PMID 33816262, 2021). "Consistently, we also noticed that the expression of ATG7 and BECN1 were predominantly located at the tumor edge rather than tumor nest by IHC in these tumor tissues." (PMID 34483138, 2021). "Since LAP involves autophagy genes such as ATG5, ATG7 and BECN1 but not FIP200, it represents a distinct non-autophagy function of these other autophagy genes that can impinge on anti-tumor immunity." (PMID 32743346, 2020).
tumor (continued). "Finally, treatment with rapamycin induced LC3-II, ATG7, ATG12 and Bcl2 expression and reduced the levels of SQSTM1/p62 and Bax, indicating that autophagy can protect tumour cells from the negative effects of HMGA2 knockdown." (PMID 31053152, 2019).
cancer (173 papers, 2011 to 2026). A tumor composed of atypical neoplastic, often pleomorphic cells that invade other tissues. "In another study by Nuta and colleagues, the authors reported a cancer-associated mutation in LC3 which affects binding to ATG7 and its function in LC3 conjugation." (PMID 35867735, 2022). "Our data demonstrated that expression of cancer associated ATG7 variants resulted in p62 accumulation in cholangiocyte cells under metabolic stress paralleling a tumorigenic environment." (PMID 35725745, 2022). "Loss of ATG5 and ATG7 was found to increase basal and maximal respiration as well as proton leak in cancer cells." (PMID 34885250, 2021). "In one instance, it was shown that deletion of ATG7 leads to metabolic and proliferative problems in cancer, causing cancer cells to become more sensitive to starvation and more dependent on glutamine." (PMID 34835393, 2021). "The NRF1 ChIP-seq data from the ENCODE project confirms the binding of NRF1 to ATG5 and ATG7 promoter regions in 4 different cancer cells (HepG2, K562, SK-N-SH, and HeLa-S3 cell lines)." (PMID 34458153, 2021). "We show that knockdown of the ribosomopathy factor SBDS, or of key ribosome biogenesis factors (PPAN, NPM, PES1) is associated with enhanced levels of ATG7 in cancer cells." (PMID 34944838, 2021). "In liver tumorigenesis, Beclin 1, a haplo-insufficient gene has been implicated, similarly, ATG 5, ATG7 and p62 are also found to have important tumorigenic role, and suppression of these genes can reduce cancer progression." (PMID 33311531, 2020). "Molecular mechanisms underlying Atg8 lipidation remain poorly understood despite association of Atg3, the E1 Atg7, and the composite E3 Atg12–Atg5-Atg16 with pathologies including cancers, infections and neurodegeneration." (PMID 31399562, 2019). "Atg5-deficiency, Atg7-deficiency, and Beclin-1 partial deletion can spur spontaneous tumor growth commonly seen in most cancers." (PMID 29988591, 2018). "This was related to the maintenance of cancer stem cells since IL-6 supplementation increased mammosphere formation in ATG7 shRNA-expressing cells and was associated to dependence on autophagy for survival." (PMID 30622432, 2018). "Results showed that hernandezine exhibited less cytotoxicity in Atg7-deficient MEFs when compared to their wild-type counterparts, similar results were found in HeLa cancer cells with Atg7 knockdown." (PMID 26811496, 2016). "This alkaloid-induced cellular toxicity is associated with the up-regulation of Atg7-dependent autophagy, which is potentially beneficial to anti-cancer therapy." (PMID 26811496, 2016). "It is clarified that knock down of Atg5 or Atg7 causes impairment of autophagy system associated with apoptosis of cancer cells and inhibition of cell growth." (PMID 24725767, 2014). "Moreover, we detected somatic deletion of ATG7 and loss of heterozygosity among the cancers in this family." (PMID 35725745, 2022). "However, mutations of autophagy-related genes such as ATG5 and ATG7 are rare and autophagy can be activated in cancer cells under various stress conditions, indicating autophagy-independent regulation implicated in p62 expression." (PMID 33854041, 2021). "These approaches will also help to ascertain whether ATG7‐deficient individuals are at altered risk of diseases such as neurodegeneration, cancer and infection compared with the general population, improving our understanding of complex human disorders." (PMID 34725936, 2021). "Yet, other core autophagy genes, including ATG7, are rarely mutated in human cancers." (PMID 34725936, 2021). "As for radiotherapy, ATG7 deficiency could sensitize cancer cells to IR." (PMID 36105209, 2022). "In addition, ATG7 is identified as a cancer susceptibility gene for cholangiocarcinoma." (PMID 35585060, 2022).
cancer (continued). "Studies have shown that the downregulation of autophagic genes like ATG5 or ATG7 inhibits tumour growth and enhances apoptosis, underscoring the indispensable role of autophagy in sustaining cancer cell growth." (PMID 39863836, 2025). "The implication of ATG7 in cancer is further complicated by its autophagy-independent ability to modulate cell cycle arrest and apoptosis and modulate the efficacy of anticancer treatments." (PMID 40707430, 2025). "In this study, patients from the cancer genome altas (TCGA) COAD/READ cohorts were used to investigate the biological mechanism driving ATG7 development." (PMID 38627815, 2024). "Emerging studies have shown that miRNAs can directly inhibit Atg7 in some key pathways involved in drug resistance in cancer." (PMID 38553562, 2024). "ATG7 is an autophagy-related protein whose aberrant expression and its relationship with cancer are not yet fully understood." (PMID 39464718, 2024). "Autophagy-related protein 7 (ATG7) plays an important role in autophagy and it has been linked to cancer." (PMID 38627815, 2024). "In a model of lung cancer, knockdown of ATG5, BECN1, ATG7 and p62/SQSTM1 decreases A549 cell invasiveness in the presence of cancer-associated fibroblasts (CAFs)." (PMID 37887330, 2023). "Although autophagy depletion and genetic deletion of ATG5 and ATG7 initiate tumors in mice, these interventions ultimately slow the progression of malignant tumors in tissue-specific cancer models derived from various oncogenes." (PMID 38067169, 2023). "This suggests that there are functions of ATG7 in cancer that are autophagy-independent, and which are dependent on the dosage of the gene." (PMID 35867735, 2022). "Consistent with an overall close correlation between copy number and mRNA expression, the copy numbers of BECN1 and ATG7 correlated significantly with mRNA levels across the entire pan-cancer dataset comprising 9889 patient tumors." (PMID 35681458, 2022). "In NSCLC, high hsa_circ_0085131 levels activated the hsa_circ_0085131/miR-654-5p/Autophagy Related 7 (ATG7) axis and cell autophagy to enhance cancer cell cisplatin resistance." (PMID 35205613, 2022). "To this end, we found that while SRC inhibitors promote cell death in cancer cells harboring oncogenic SRC, simultaneous inhibition of autophagy (by hydroxychloroquine or by ATG5 or ATG7 knockout) promotes apoptosis of cancer cells even further." (PMID 35647611, 2022). "The potential molecular mechanism by which autophagy of SCs promotes PNI in PanCa is that neurotrophic factors, such as NGF, secreted by cancer cells can induce autophagy of SCs by upregulating ATG7 expression." (PMID 35109895, 2022). "The combination of BRAF, CRAF, and ATG7 depletion was most successful in reducing cancer cell viability." (PMID 34830283, 2021). "Previous study have shown that down-regulated ATGs, including ATG4(also know as LC3B) and ATG7, synergized the anti-cancer function of chemotherapy." (PMID 34253689, 2021). "The effect of NJXA on inducing mitophagy and inhibiting cancer cell proliferation was abolished by knocking down the mitophagy regulator ATG7 and enhanced by the mitophagy-induced environment induced by nutrient starvation." (PMID 34065886, 2021). "In our study, expression of ATG12 and ATG7 showed up-regulation while ATG10 expression was down regulated in cancer tissues." (PMID 33604190, 2021). "In yeast, flies, worms, and human immune and cancer cells, histone and chromatin modifications regulate Atg7 expression." (PMID 32043463, 2020).
cancer (continued). "ANXA6 or Atg7 knockdown stimulated cancer cell proliferation to a greater extent than wild‐type cells based on the results of cell growth curves and colony formation assays." (PMID 33135350, 2020). "Among miR-582-5p direct targets is also ATG7—an E1-like activating enzyme involved in autophagy, which is often activated as a protective mechanism of resistant cancer cells during chemotherapy." (PMID 32756406, 2020). "Cetuximab, a therapeutic antibody that blocks the function of epidermal growth factor receptor, induced apoptosis and autophagy, and the knockdown of ATG7 or Beclin1 or treatment with CQ sensitized cancer cells to cetuximab-triggered apoptosis." (PMID 33239065, 2020). "In a panel of cancer cell lines, cell death increased upon knockdown of Beclin1 or ATG7 genes, suggesting a role of autophagy in cell survival within hypoxic regions." (PMID 32547395, 2020). "Disruption of autophagy by depleting Atg7 or Atg5 induces cellular senescence and reduces cancer burden in these diseases." (PMID 32807225, 2020). "The knockdown of ATG7 in human BC cells dramatically inhibits cancer cell invasion, revealing that ATG7 is a key player in regulating BC invasion." (PMID 31016112, 2019). "Studies in human cancer cell lines revealed that knockdown of ATG7, crucial for LC3-II formation, results in reduced glycolysis and vice versa." (PMID 31036602, 2019). "Of note, blocking of neferine-mediated autophagy by siRNA knockdown of Atg7 in this apoptosis-resistant Bax-Bak DKO DLD-1 cancer cells would suppress the cytotoxic effect of neferine." (PMID 31882989, 2019). "The biological role of overexpressed ATG7 is demonstrated by knockdown of ATG7 in human BC cells, which show a dramatical inhibition of BC cancer cell invasion." (PMID 31016112, 2019). "Tanshinone IIA, one of the main compounds of S. miltiorrhiza Bunge, has been shown to inhibit the growth of cancer cells via autophagy and apoptosis, which is related to the Beclin-1/Atg7/Atg12-Atg5 and PI3K/Akt/mTOR pathways." (PMID 31406500, 2019). "The analysis of multiple cancers showed the overexpression of ATG5 in gastric and prostate cancers while overexpression of ATG7 was seen in bladder cancer." (PMID 29643976, 2018). "Indeed, in the ATG7 knockout model, the loss of p62 was associated with marked reduction of ubiquitin-positive inclusions and oxidative stress, suggesting that aggregation depends on p62 and that p62 aggregation may exacerbate stress in cancer cells." (PMID 30067838, 2018). "Collectively, our findings suggested that thalidezine-induced autophagy requires Atg7 and it promotes autophagic cell death in cancer cells." (PMID 28404910, 2017). "Hernandezine-induced autophagy requires the involvement of Atg7 and promotes cell death in cancer cells." (PMID 26811496, 2016). "We previously reported that autophagy occurs after cetuximab treatment and that knockdown of autophagy regulatory genes, such as Beclin 1 or Atg7, or treatment with the lysosome inhibitor chloroquine sensitized cancer cells to cetuximab-induced apoptosis." (PMID 25871473, 2015). "Prompted by the clues from model organisms, the architecture of the functional ATG7-mediated regulatory network has been explored in the settings of human biology and disease, such as cancer, infectious disease, and neurodegenerative diseases." (PMID 26404030, 2015). "Our results are consistent with other reports that autophagy inhibition by CQ or other autophagy inhibitor (e.g., ATG-5 siRNA and ATG-7 siRNA) induces cell death in cancer cell types." (PMID 24581180, 2014). "It has been clarified that impairment of autophagy system by knocking down Atg5 or Atg7 induces apoptosis of cancer cells, inhibiting cell growth." (PMID 24725767, 2014). "ATG7, a key protein in autophagosome formation, plays a crucial role in cancer." (PMID 39863836, 2025). "It has been demonstrated that Atg7 can be genetically targeted to stop this enzyme in cancer cells." (PMID 40248706, 2025).